FAM181B (family with sequence similarity 181 member B)
Synonyms: LOC220382; MGC33846
Tractability: No criterion of Open Targets' tractability assessment is met for any kind of drug.
Gene: Protein-coding gene on chromosome 11 (82,729,940 to 82,733,864, reverse strand). Ensembl gene ENSG00000182103.
Subcellular location (Human Protein Atlas): Mitochondria; Nuclear membrane
Genetic constraint (gnomAD): Loss-of-function variants: 13 observed, 10.19 expected, observed/expected ratio (o/e) 1.28, 90% interval 0.82 to 1.85. The synonymous counts are far from expectation, so gnomAD's model fits this gene poorly and the ratio says little. Missense variants: 725 observed, 468.63 expected, observed/expected ratio (o/e) 1.55, 90% interval 1.46 to 1.64. Synonymous variants: 338 observed, 234.94 expected, observed/expected ratio (o/e) 1.44, 90% interval 1.32 to 1.57.
Homologues: Orthologues: chimpanzee FAM181B (99% identical), macaque FAM181B (96% identical), pig FAM181B (87% identical), dog FAM181B (84% identical), mouse Fam181b (77% identical), rat Fam181b (76% identical), tropical clawed frog FAM181B (33% identical). Paralogues in human: FAM181A (17% identical).
Diseases named in the same sentence as FAM181B in open-access papers:
FAM181B is named in the same sentence as 1 disease in open-access papers, as found by Europe PMC text mining. Sharing a sentence is not in itself a finding about the gene and the disease.
FAM181B shares sentences with these, for which no sentence is quoted: Alzheimer disease (1 paper).